MAVS (mitochondrial antiviral signaling protein)
Diseases named in the same sentence as MAVS in open-access papers (continued):
Sharing a sentence is not in itself a finding about the gene and the disease.
pneumonia (1 paper, 2024). An acute, acute and chronic, or chronic inflammation focally or diffusely affecting the lung parenchyma, caused by an infection in one or both of the lungs (by bacteria, viruses, fungi, or mycoplasma.). "To further substantiate our observation that RIG-I/MAVS pathway activation is required for Pam2ODN-induced antibacterial protection, we developed a similar model of pseudomonal pneumonia with reduced lethality (2 × 1010 CFU/mL vs. 2.5 × 109 CFU/mL)." (PMID 39352770, 2024). "ODN binding by RIG-I resulted in MAVS-dependent pneumonia-protective signaling events." (PMID 39352770, 2024).
respiratory syncytial virus infection (1 paper, 2020). "During respiratory syncytial virus infection, NOD2, but not NOD1, can sense single-stranded RNA (ssRNA) from the virus and interacts with mitochondrial antiviral signaling (MAVS)." (PMID 32778560, 2020).
rosacea (1 paper, 2021). A chronic erythematous skin disorder that affects the face. "In inflamed psoriatic and rosacea skin, the RIGI/MAVS signaling pathway is activated upon recognition of the self nucleic acids by cathelicidin, which leads to activation of a downstream type 1 interferon response and adaptive priming to dendritic cell–mediated T cell activation." (PMID 34048712, 2021).
Salmonella Infections (1 paper, 2023). Infections with bacteria of the genus SALMONELLA. "Among the multiple genes detected in this study, EXFABP, S100A9/12, CEMIP, FKBP5, MAVS, FAM168B, HESX1, EMC6, and others were found as potential candidate gene and transcript (co-) factors for resistance to Salmonella infection." (PMID 36902251, 2023).
steatosis (1 paper, 2025). Increased lipid within the cytoplasm of cells. "Overall, our results point toward MAVS as a molecule implicated in the development of steatosis." (PMID 38761407, 2025). "The scoring system of qualitative analyses for steatosis grade, lobular inflammation, liver injury, and fibrosis stage showed that the inhibition of MAVS in the liver improved the liver status." (PMID 38761407, 2025). "MAVS is involved in the development of steatosis, and its inhibition in previously damaged hepatocytes can ameliorate MASLD." (PMID 38761407, 2025). "In both in vitro and in vivo settings, MAVS overexpression increased hepatocyte lipid accumulation, while MAVS inhibition relieved TAp63- and diet-induced steatosis." (PMID 38761407, 2025). "Moreover, our in vitro and in vivo genetic functional studies indicated that overexpression of MAVS induces lipid deposition while its silencing alleviates steatosis." (PMID 38761407, 2025). "Notably, we present preliminary functional data demonstrating that silencing MAVS genetically or inhibiting its O-GlcNAcylation through pharmacological means effectively prevents steatosis and MASLD development." (PMID 38761407, 2025). "We analyzed whether MAVS inhibition would affect TAp63-induced steatosis in mice." (PMID 38761407, 2025).
T-cell lymphoma (1 paper, 2023). "Cross-referencing the Degrabase dataset against the mtRNA signaling pathway identified in this study reveals MAVS and IRF3 as potentially relevant targets for apoptotic caspase cleavage in Jurkat T-cell lymphoma cells." (PMID 36918588, 2023).
infection (357 papers, 2008 to 2026). The state of being infected such as from the introduction of a foreign agent such as serum, vaccine, antigenic substance or organism. "When IFN-I signaling was blocked by antibody, MAVS-deficient mice lost significant weight, but were uniformly protected from lethal disease, whereas all control mice succumbed to infection." (PMID 35587473, 2022). "Overall, these results reveal the molecular mechanism underlying aMPV/C infection-induced MAVS degradation by the ubiquitin-proteasome pathway." (PMID 34696420, 2021). "The immunoprecipitation results showed that aMPV/C infection promoted the formation of MAVS polyubiquitin chains and K48-linked ubiquitination in the aMPV/C-infected Vero cells treated with MG132." (PMID 34696420, 2021). "The results showed that the cells infected with aMPV/C at an MOI of 0.5 showed more reduction in MAVS than that at an MOI of 0.1, indicating that aMPV/C infection caused the decrease in MAVS protein expression in a dose-dependent manner." (PMID 34696420, 2021). "Sites for attachment of K48-linked ubiquitination near residues K7 and K420 in human MAVS, leading to proteasomal degradation after infection, are conserved between species." (PMID 32272772, 2020). "MAVS deficiency resulted in a 0.5 to 1.0 log10 increase in bacterial burden in the lung at 3, 5, 8 and 12 weeks post-infection when compared to WT infected mice." (PMID 32463840, 2020). "Infection of MAVS-deficient mice (MAVSKO mice) with West-Nile Virus (WNV), a single-stranded RNA virus of the flavivirus family, results in a dysregulated adaptive immune response." (PMID 33104760, 2020). "In vitro infection assays demonstrated that PBMCs obtained from donors carrying the MAVS minor genotype were less susceptible to HIV-1 replication." (PMID 32708557, 2020). "To overcome these limitations, we have infected MAVS-deficient (MAVSKO) mice with a single-round-of-infection mutant of West Nile virus." (PMID 33104760, 2020). "After footpad inoculation with 100 PFU of WNV-MAD, MAVS-deficient mice survived infection and showed only occasional mild disease symptoms." (PMID 31242236, 2019). "MAVS-/- mice all succumb to pathogenic lineage 1 WNV-TX infection within 8–9 days due to their inability to control virus replication and spread into the central nervous system." (PMID 31242236, 2019). "Meanwhile, another study revealed that EV-A71 infection caused morphologic and functional changes of the mitochondria, whereby in vitro cleavage assay indicated that EV-A71 approached MAVS and led to MAVS cleavage by 2Apro." (PMID 30349526, 2018). "rJHMVWT caused a lethal infection in MAVS−/− mice, but rJHMVPS− remained attenuated, causing moderate weight loss and no decrease in survival." (PMID 29717007, 2018). "Although ER/mitochondrial contacts have been implicated in the MAVS signaling pathway, the number of peptides identified from the fission machinery were unaltered upon infection." (PMID 28273895, 2017). "During poliovirus infection, human PVR transgenic TICAM-1−/− mice showed a higher susceptibility to infection compared with wild type and MAVS−/− transgenic mice." (PMID 26694447, 2015). "PCBP2 sumoylation mediated by IRTKS took place in the nucleus on RNA virus infection, which causes its cytoplasmic translocation to interact with MAVS during the late stage of infection, leading to MAVS degradation." (PMID 26348439, 2015). "Similar results have been obtained in an in vivo model of infection, where MAVS deficient mice produced reduced amount of type I IFN in response to RSV infection." (PMID 24244872, 2013). "In ISG15 knock-down cells, the RIG-I/MAVS association occurred later at 6 hrs post-infection with an increase in TRAF3 association at 9–12 hrs post infection." (PMID 22022264, 2011). "Mice deficient in MAVS are severely compromised in host defense against infection of several viruses." (PMID 22110409, 2011).
infection (continued). "A MAVS-dependent signal is thus induced upon infection with MVA orMVAΔF1L, which causes the IRF-3-dependent up-regulation of Noxa and apoptosis." (PMID 21698224, 2011). "The PKR/MAVS association took place at 4 hrs post-infection in the control cells but was observed 2 hrs earlier in the ISG15-depleted cells." (PMID 22022264, 2011). "The diminished lytic replication of γHV68 in MAVS-deficient MEFs is consistent with the reduced acute infection observed in the lung." (PMID 20686657, 2010). "Furthermore, individuals with the CC and CA genotypes at MAVS rs16989000 have a higher risk of infection compared to those with the AA genotype." (PMID 40331958, 2025). "In future studies it will be interesting to address whether the pool of presented peptides differs in MAVS deficient and competent microglia under conditions of infection and inflammation." (PMID 40619428, 2025). "Together, these results demonstrate that MAVS is cleaved during infection and the close proximity of MAVS and Mpro could leave MAVS susceptible to Mpro cleavage." (PMID 38400032, 2024). "Additionally, recruitment and activation of mitochondrial antiviral-signaling protein (MAVS) triggered by cytoplasmic sensing of virus RNA was also associated to cell death in in vitro infection models." (PMID 35185902, 2022). "To determine the pattern of MAVS ubiquitination in aMPV/C-infected Vero cells, we co-transfected Vero cells with plasmids encoding Flag-MAVS or Flag and HA-Ub-K48 or HA-Ub-K63, followed by aMPV/C infection and an immunoprecipitation assay." (PMID 34696420, 2021). "We determined whether immune activation and CTL activity are associated with the protective effect of the MAVS minor genotype during the asymptomatic phase of infection." (PMID 32708557, 2020). "Similarly, MAVS–/– mice were shown to be highly susceptible to DENV (serotype 2) infection and showed delayed IFN-α and IFN-β production." (PMID 31652496, 2019). "To determine whether viral counteraction of MAVS is affected by its subcellular localization we employed infection of cells with HCV, a major causative agent of chronic liver disease with a high propensity to establish persistence." (PMID 26588843, 2015). "Our results show that RSV NS1 is associated with mitochondrial MAVS during infection, thus inhibiting MAVS-RIG-I interaction which might indirectly affect IFN production." (PMID 22383950, 2012). "However, the presence of TRAF3 in association with MAVS at 2 hrs post-infection in the control cells correlates with its association with PKR which indicates that the MAVS pathway can be activated through PKR as soon as 2 hrs post infection." (PMID 22022264, 2011). "Mitochondrial ROS (mtROS), mitochondrial antiviral signaling protein (MAVS) and mitochondrial damage-associated molecular patterns (mtDNA, mtTFA, N-formyl peptides, cardiolipin) play key roles in the activation of innate immune response following infection or tissue damage." (PMID 28507507, 2017). "Having excluded that MAVS deficiency elevates the intrinsic cytokine production by macrophages, we surmised that the elevated cytokines in γHV68-infected Mavs−/− mice, at least during early infection (e.g., 7 d.p.i.), are likely produced by lung epithelium/fibroblasts." (PMID 22110409, 2011). "The results showed that a significant decrease of endogenous MAVS expression level was detected at 72 h EIAVCMV3-8 post-infection (hpi) in a dose-dependent manner." (PMID 39665545, 2025). "In summary, we identified the deubiquitinase USP35 as a host factor modulating MAVS activity during the infection of RNA viruses." (PMID 40016186, 2025). "By inhibiting MAVS, the coronavirus is able to reduce the production of IFNs in the early stages of infection, creating favorable conditions for the spread of the virus and the development of the disease." (PMID 41472136, 2025).
infection (continued). "Infection-related ORF3c (41 residues) interferes with MAVS signalling at mitochondria by interacting with MAVS and PGAM5, a regulator of mitochondrial dynamics." (PMID 41394882, 2025). "Our result showed that EIAV (EIAVDLV34) infection is able to attenuate IFN-β expression through MAVS in the eMDMs (right)." (PMID 39665545, 2025). "First, we examined phosphorylation of MAVS upon infection with RNA viruses such as Sendai virus (SeV) or vesicular stomatitis virus expressing green fluorescent protein (VSV-GFP)." (PMID 40837220, 2025). "Others report that Trim7 ubiquitinates stimulator of interferon genes (STING) and mitochondrial antiviral signaling protein (MAVS), leading to a reduced innate immune response and decreased protection against infection." (PMID 40464581, 2025). "Immunoblot analysis revealed that signals detected by the MAVS p-S220 antibody were significantly enhanced in response to infection with either virus, indicating a potential role for MAVS phosphorylation in antiviral responses." (PMID 40837220, 2025). "Trim7 has been reported to influence host innate immune defenses due to its role in the degradation of STING and MAVS, leading to decreased inflammatory response to infection." (PMID 40464581, 2025). "Our results demonstrated that infection with IAV-H1N1 led to an increase in the ubiquitination of MAVS along with promoted expression of TRIM22." (PMID 40162781, 2025). "This implies that either 3Cpro-mediated cleavage of MAVS is relatively inefficient and only occurs very late in infection, or that initial 2Apro-mediated cleavage is required to facilitate further proteolytic cleavage by 3Cpro." (PMID 40875754, 2025). "For example, MDA5 was found to sense fungal dsRNA in the cytosol of macrophages during infection by Aspergillus fumigatus in mice, resulting in a protective MAVS‐mediated type I IFN response." (PMID 39620586, 2025). "In contrast, the number and composition of EVs released by MAVS KO cells remained comparable to that observed in WT cells upon infection with either virus." (PMID 38662794, 2024). "In summary, this data shows that MAVS signaling is crucial for viral restriction and containment of the infection in the NC and proximal regions of the CNS." (PMID 39425188, 2024). "A limitation of our study is that most of our results were obtained by overexpressing proteins and therefore the role of USUV NS4A in inhibiting MAVS signaling in the context of infection remains to be studied." (PMID 38969013, 2024). "To confirm these results, we stably knocked-down the expression of RIG1, IFIH1 and MAVS with shRNAs by lentiviral infection." (PMID 38383514, 2024). "FMDV replicates its RNA genome in the cytosol where innate immune RNA sensors recognize foreign RNA molecules derived from infection to activate the RLR/MAVS or TLR routes and induce the innate immune response in the host." (PMID 38509419, 2024). "Ideally, one would inhibit Mpro during infection to formally prove that Mpro is responsible for cleaving MAVS." (PMID 38400032, 2024). "During infection, MAVS is not only targeted for degradation by the virus, but there are also cellular mechanisms in place that keep MAVS activation at bay to prevent excessive activation of the immune response." (PMID 38400032, 2024). "We then stained both mock-infected and infected cells for MAVS and the mitochondrial marker TOMM20 and found that MAVS still localized to the mitochondria, but the morphology of the mitochondria had changed upon infection." (PMID 38400032, 2024). "Depletion of MAVS resulted in a near complete reduction of IFNβ secretion following infection with YFV-17D or DENV2." (PMID 39282299, 2024). "Though σ3 protein would complex with MRV μ1 to form a heterohexamer during MRV infection, we found that σ3 protein retains the capacity to interact with and degrade MAVS in the presence of μ1." (PMID 38757961, 2024).
infection (continued). "The activation of NOD2 during the infection leads to interaction with MAVS and elicits the secretion of IFN-α." (PMID 38668261, 2024). "Altogether these data indicate that 4-OI promotes VSVΔ51 infection in cancer cells through the direct targeting of two critical proteins in the interferon signaling pathway, MAVS and JAK1." (PMID 38750019, 2024). "RLR signal transduction occurs through CARD-carrying downstream signaling factor MAVS, which also forms puncta inside cells upon infection." (PMID 38980902, 2024). "It has been shown that over-expression of MAVS in teleost fish protects cells from infection by both DNA and RNA viruses by inducing IFN stimulated genes (ISGs), such as IRF3 and the myxovirus resistance (Mx) as well as type I IFN." (PMID 37622112, 2023). "It is worth noting that the antiviral signaling protein Mitochondrial Antiviral Signaling Protein (MAVS) decreased mRNA level in cells after infection with YT strain." (PMID 37063902, 2023). "Similar to VHSV IVb, Ia strain shuts down IFN and MX1 induction in cells over-expressing MAVS or treated with exogenous IFN prior to infection." (PMID 36851680, 2023). "In contrast, SAV3 infection resulted in massive CPE in the MAVS, IRF3, and IRF7-1/3 KOs, which suggests an increased SAV3 replication." (PMID 37588594, 2023). "As MAVS increases during infection, the positive regulation by this SERINC5-independent mechanism apparently prevails over the negative effect of reducing SERINC5 (SERINC5-dependent mechanism)." (PMID 36876111, 2023). "On the contrary, they progressively increased, suggesting that a SERINC5-independent mechanism would be responsible for the augmentation in MAVS during infection." (PMID 36876111, 2023). "In vitro studies indicate that RSV N induces the formation of inclusion bodies that serve as ‘traps’ for MAVS and melanoma-differentiation-associated gene 5 (MDA-5) during an early stage of infection." (PMID 37896776, 2023). "Since both DNA and RNA sensors trigger IRF3‐mediated type‐I IFN signaling, we considered why the MDA5/MAVS‐deficient, or cGAS/STING‐deficient, mice responded to N67C infections differently." (PMID 35635376, 2022). "IAV polymerase complex subunit PB1 can mediated RNF5 and NBR1-depandent autophagic degradation of MAVS to disrupt MAVS -medicated innate signalling pathway at the early infection." (PMID 34967267, 2022). "Flow cytometry analysis revealed significantly higher levels of infection in cGAS‐KO cells compared to WT and MAVS‐KO cells at both time points." (PMID 35670106, 2022). "Consistent with being a determinant of infection outcomes, MAVS displays strong signatures of rapid evolution in primate genomes, which includes positively selected sites proximal to the NS3/4A protease target site shown to impact cleavage." (PMID 35073751, 2022). "We next sought to determine if MAVS was required for the induction for pro-inflammatory responses not only in CD169-mediated abortive infection but also in ACE2-mediated productive infection of macrophages with SARS-CoV-2." (PMID 36279285, 2022). "To assess the presence of infectious virus, we used Huh7-Lunet CD81 cells stably expressing the MAVS-GFP-NLS reporter allowing for a sensitive detection of infection events in living cells." (PMID 35763545, 2022). "This activated complex of RIG-I and MAVS (RIG-I:MAVS) serves as the intersection of multiple innate immune pathways that are simultaneously activated to respond to the infection, notably the interferon (IFN) and nuclear factor κB (NFκB) pathways." (PMID 36146870, 2022). "Following infection with VSV-GFP, although loss of MAVS partly impaired the antiviral effects of Rig-ifs/fs MEFs, the lower percentage of GFP+Rig-ifs/fs MEFs was observed when endogenous MDA5 was silenced as compared with wild-type MEFs." (PMID 36402769, 2022). "Levels of viral genome in the liver and serum on day 4 post-infection were reduced in mAb-5A3 treated MAVS KO mice compared to WT mice treated with mAb-5A3." (PMID 35587473, 2022).